MYO16 (myosin XVI)
Description:
Myosins are actin-based motor molecules with ATPase activity. Unconventional myosins serve in intracellular movements. Their highly divergent tails are presumed to bind to membranous compartments, which would be moved relative to actin filaments. May be involved in targeting of the catalytic subunit of protein phosphatase 1 during brain development. Activates PI3K and concomitantly recruits the WAVE1 complex to the close vicinity of PI3K and regulates neuronal morphogenesis (By similarity).
Synonyms: KIAA0865; MYO16B; NYAP3; MYR8; PPP1R107; MYAP3
Tractability: Antibody: its Gene Ontology location is reachable by antibodies, with medium confidence. PROTAC: ubiquitination databases record sites on it; its protein half-life has been measured.
Gene: Protein-coding gene on chromosome 13 (108,596,152 to 109,208,005, forward strand). Ensembl gene ENSG00000041515.
Subcellular location: Cytoplasm
Subcellular location (Human Protein Atlas): Vesicles
Gene Ontology:
Molecular function: protein binding; actin filament binding; protein phosphatase binding; ATP binding; cytoskeletal motor activity
Biological process: cerebellum development; negative regulation of cell population proliferation; negative regulation of G1/S transition of mitotic cell cycle; neuron projection morphogenesis; phosphatidylinositol 3-kinase/protein kinase B signal transduction
Cellular component: nucleoplasm; perinuclear region of cytoplasm; cytoplasm; myosin complex; plasma membrane
Genetic constraint (gnomAD): Loss-of-function variants: 72 observed, 151.79 expected, observed/expected ratio (o/e) 0.47, 90% interval 0.39 to 0.58. The upper end of that interval is the gene's LOEUF score, 0.58, which puts it in group 2 of 6, group 1 being the genes least tolerant of losing a copy. Missense variants: 2,091 observed, 2,057.4 expected, observed/expected ratio (o/e) 1.02, 90% interval 0.98 to 1.05. Synonymous variants: 909 observed, 828.1 expected, observed/expected ratio (o/e) 1.1, 90% interval 1.04 to 1.16.
Homologues: Orthologues: chimpanzee MYO16 (99% identical), macaque MYO16 (97% identical), rat Myo16 (77% identical), mouse Myo16 (76% identical), guinea pig MYO16 (68% identical), tropical clawed frog myo16 (61% identical), zebrafish myo16 (42% identical). Paralogues in human: MYO3A (21% identical), MYO3B (20% identical), MYO15A (18% identical), MYO10 (17% identical), MYO7A (16% identical), MYO7B (16% identical), MYH3 (16% identical), MYH7 (16% identical), MYH2 (16% identical), MYH6 (16% identical), MYH7B (16% identical), MYH1 (16% identical), and 32 more.
Diseases named in the same sentence as MYO16 in open-access papers:
MYO16 is named in the same sentence as 34 diseases in open-access papers, as found by Europe PMC text mining. Sharing a sentence is not in itself a finding about the gene and the disease. The quoted sentences say what the papers report.
schizophrenia (4 papers, 2016 to 2021). A major psychotic disorder characterized by abnormalities in the perception or expression of reality. "Previous evidence suggested that common variants within the MYO16 gene contribute to the genetic liability of schizophrenia." (PMID 27450446, 2016). "As a support of this, the genetic examinations underscore the significance of Myo16 in the pathomechanism of neurological disorders, such as schizophrenia, autism spectrum disorder, bipolar disorder subtype II and major depressive disorder." (PMID 32824179, 2020). "Importantly, genetic evidence also indicates links of MYO16 to schizophrenia and to bipolar disorder." (PMID 31474830, 2019).
prostate carcinoma (3 papers, 2024 to 2025). A carcinoma that arises from epithelial cells of the prostate gland. "One candidate variant in MYO16 was tested in the previous study and had a positive OR = 1.24, supporting an increased risk of CRC and possibly also gastric and/or prostate cancer." (PMID 39859530, 2025). "Highly expressed genes defining the IDCP cluster, such as MUC6, MYO16, NPY, and KLK12, reflected the aggressive nature of high-grade prostate cancer." (PMID 38732035, 2024).
colorectal cancer (2 papers, 2021 to 2024). A primary or metastatic malignant neoplasm that affects the colon or rectum. "The mutation of MSH6, for example, may increase the risk of developing colorectal carcinomas, and MYO16 appears to have an important role in neural development and the function of the nervous system." (PMID 33451291, 2021).
diabetic nephropathy (2 papers, 2013 to 2015). "The MYO16 (myosin XVI) locus has recently been implicated in diabetic nephropathy." (PMID 23509613, 2013).
Obesity (2 papers, 2018 to 2020). Accumulation of substantial excess body fat. "This resulted in 1758 variables selected using collective feature selection (note that intersection of methods only selects 2 genes which do not include well known SNPs linked to obesity such as variants in FTO and MYO16)." (PMID 29713383, 2018).
type 2 diabetes (2 papers, 2013 to 2015). "Three of these loci, located on chromosome 9q21.32 near the FRMD3 gene, chromosome 11p15.4 at the CARS gene, and chromosome 13q33.3 at the MYO16/IRS2 locus, have since been confirmed in multiple diverse collections of unrelated T1D or type 2 diabetic (T2D) patients." (PMID 23555951, 2013).
Alzheimer disease (1 paper, 2018). A progressive, neurodegenerative disease characterized by loss of function and death of nerve cells in several areas of the brain leading to loss of cognitive function such as memory and language. "TTBK1 is also known to be associated with Alzheimer’s disease while MYO16 has been found to be associated with pulse pressure." (PMID 29713383, 2018).
Anxiety (1 paper, 2019). Intense feelings of nervousness, tension, or panic often arise in response to interpersonal stresses. "In the open field test, Myo16–/– mice were indistinguishable from wild-type littermate controls in terms of locomotor activity (total distance moved, velocity) and regarding a measure of anxiety (mean distance to wall)." (PMID 31474830, 2019).
autism (1 paper, 2015). Persistent deficits in social interaction and communication and interaction as well as a markedly restricted repertoire of activity and interest as well as repetitive patterns of behavior. "Genetic association has been found between the MYO16 gene and autism in two large cohorts (AGRE and ACC) of European ancestry and replicated in two other cohorts (CAP and CART)." (PMID 25902260, 2015). "Furthermore, a genome wide association study suggested a potential autism association signal at 13q13.3 near MYO16." (PMID 25902260, 2015). "In addition, we found a genomic deletion encompassing MAP1B in one patient with intellectual disability, microcephaly and seizures and deletions encompassing MYO16 in two unrelated patients with intellectual disability, autism and microcephaly." (PMID 25902260, 2015).
Autoimmunity (1 paper, 2021). The occurrence of an immune reaction against the organism's own cells or tissues. "Interestingly, not far from MYO16, in the chr13:108090996-108968251 region highlighted by HH analysis, is located the TNFSF13B gene, encoding the cytokine and drug target B-cell activation factor (BAFF) whose overexpression is related to autoimmunity." (PMID 34889895, 2021).
breast carcinoma (1 paper, 2024). "MYO16 has been suggested as one candidate after linkage analysis in familial breast cancer and MYO16-AS in the same haplotype has been described to act in both bladder and lung cancer." (PMID 39543761, 2024).
COVID-19 (1 paper, 2024). A disease caused by infection with severe acute respiratory syndrome coronavirus 2. "We found three new-onset autoantibodies associated with increased severity of neuropsychiatric symptoms post-COVID-19: anti-CALU, MYO16, and SNURF IgG." (PMID 39414823, 2024).
T-cell lymphomas (1 paper, 2014). "Similarly the targeting of novel genes that were not seen in previous large-scale screens of MoMLV-induced T-cell lymphomas (e.g. Otx2, Myo16) is not merely due to their up-regulation in the background of the Runx2/MYC model." (PMID 24586197, 2014).
thymic carcinoma (1 paper, 2023). Thymic carcinoma (TC) is a type of thymic epithelial neoplasm characterized by a high malignant potential. "Compared with thymomas, thymic carcinomas (TCs) had a higher mutation frequency of MYO16 (33% vs. 3%, p = 0.024) and a lower frequency of ZNF729 mutations (0% vs. 35%, p = 0.044)." (PMID 36916520, 2023).
thymoma (1 paper, 2023). A neoplasm arising from the epithelial cells of the thymus. "The mutation frequency of MYO16 also had a trend to be higher in TCs than in B3 thymoma (33% vs. 0%)." (PMID 36916520, 2023). "Similarly, the mutation frequency of MYO16 had a trend to be higher in TCs than in B3 thymomas (33% vs. 0%)." (PMID 36916520, 2023). "Additionally, patients with TCs had a higher frequency of MYO16 mutation (33% vs. 3%, p = 0.024) and a lower frequency of ZNF729 mutation (0% vs. 35%, p = 0.044) than those with thymomas." (PMID 36916520, 2023). "Notably, TCs had a distinct mutation profile with a higher mutation frequency of MYO16 than thymomas and no ZNF729 mutations in this study." (PMID 36916520, 2023). "Whether it may aid in distinguishing B3 thymomas from TCs or not warrants further studies with more patients to validate the specificity of MYO16 alterations in TCs." (PMID 36916520, 2023).
neurodevelopmental disorder (1 paper, 2015). A behavioral and cognitive disorder with onset during the developmental period that involves impaired or aberrant development of intellectual, motor, or social functions. "Among unrelated patients referred for clinical diagnostic testing who were found to have CNVs, we identified two patients with neurodevelopmental disorders and deletions encompassing the MYO16 gene and one patient with a deletion encompassing the MAP1B gene." (PMID 25902260, 2015). "Summary of CNVs involving KIRREL3 interacting proteins MYO16, MAP1B, and ATP1B1 in patients with neurodevelopmental disorders." (PMID 25902260, 2015).
neurological disorders (1 paper, 2020). "Accordingly, the alterations of MYO16 has been linked to neurological disorders." (PMID 32824179, 2020). "In addition to the association of the MYO16 gene to neurological disorders, many binding partners of Myo16 identified so far are central to normal brain functioning." (PMID 32824179, 2020).
MYO16 also shares sentences with these, for which no sentence is quoted: cancer (2 papers); autism spectrum disorder (1); bipolar disorder (1); cardiovascular disease (1); channelopathies (1); developmental delay (1); haematopoietic cancers (1); hearing loss (1); Hypertension (1); Intellectual disability (1); lung carcinoma (1); major depressive disorder (1); medulloblastoma (1); microcephaly (1); neurodegenerative disease (1); tumor (1); type 1 diabetes (1).